TLR4 (toll like receptor 4)
Diseases named in the same sentence as TLR4 in open-access papers (continued):
Sharing a sentence is not in itself a finding about the gene and the disease.
Huntington disease (6 papers, 2018 to 2026). Huntington disease (HD) is a rare neurodegenerative disorder of the central nervous system characterized by unwanted choreatic movements, behavioral and psychiatric disturbances and dementia. "Interestingly, TLR2 and TLR4 have also been implicated in other proteinopathies, including Alzheimer’s and Huntington’s disease raising the possibility of a common pathogenic mechanism across several neurodegenerative diseases." (PMID 33272323, 2020).
intestinal tumors (6 papers, 2013 to 2022). "TLR4 activates the β-catenin signaling pathway and forms intestinal tumors, while PAK1 is associated with CRC progression and metastasis." (PMID 36406461, 2022). "According to the findings, TLR4 activation and decreased cyclooxygenase 2 regulate apoptosis in CD4-TLR4-expressing intestinal tumors." (PMID 36677399, 2022). "The molecule in the dark green and red box, respectively, indicates that the expressions of this molecule in the intestinal tumours in ApcMin/+ TLR4−/− mice were significantly lower and higher than in the intestinal tumours in ApcMin/+ WT mice." (PMID 31650683, 2020). "Based on these results, a network map of TLR4 and its regulatory genes that promoted mouse gut tissue proliferation and apoptosis in intestinal tumour formation and development was constructed." (PMID 31650683, 2020). "As a proof of principle, mice that over-express TLR4 in the intestinal epithelium have a much lower threshold for developing intestinal tumors." (PMID 23691015, 2013). "The authors attributed the pro-apoptotic effect of epithelial TLR4 activation on intestinal tumor cells to the downregulation of cyclooxygenase 2 (Cox-2), a major mediator of tumor survival and growth which can impart resistance to apoptosis, in CD4-TLR4-expressing intestinal tumors." (PMID 34479599, 2021). "It is hypothesized that the promotion of intestinal tumours by Ripk3/I‐MDSCs was mediated by TLR4/GM‐CSF signalling." (PMID 31650683, 2020).
knee osteoarthritis (6 papers, 2019 to 2025). "It is noteworthy that “TLR4” was only identified in 2015, yet it has been the subject of considerable interest in the field of knee osteoarthritis since that time." (PMID 40636390, 2025). "Curcumin supplementation can reduce inflammation in knee osteoarthritis rats by blocking the TLR4/MyD88/NF-κB signal pathway." (PMID 35662715, 2022). "Many clinical trials on curcumin supplementation have been conducted on various autoimmune diseases including osteoarthritis, and curcumin can reduce inflammation in knee osteoarthritis rats by blocking TLR4/MyD88/NF-κB signal pathway." (PMID 35662715, 2022).
myelodysplastic syndrome (6 papers, 2015 to 2022). A clonal hematopoietic disorder characterized by dysplasia and ineffective hematopoiesis in one or more of the hematopoietic cell lines. "For instance, BM stromal cells from patients with myelodysplastic syndrome display a senescence phenotype induced by S100A9-induced Toll-like receptor 4 (TLR4), NLRP3 inflammasome activation and IL-1β secretion." (PMID 33330442, 2020). "BM stromal cells from patients with myelodysplastic syndrome display a senescence phenotype induced by S100A9-induced Toll-like receptor 4 (TLR4), NLR family pyrin domain containing 3 (NLRP3) inflammasome activation, and IL-1β secretion." (PMID 33299638, 2020). "Additionally, bone marrow mononuclear and CD34+ cells from individuals with myelodysplastic syndromes, express increased levels of TLR4 when compared to the constitutive expression of TLR4 in the absence of these hematological syndromes." (PMID 26555697, 2015).
prostatitis (6 papers, 2012 to 2025). An infectious or non-infectious inflammatory process affecting the prostate gland. "In this review, we have summarized key features of the TLR4 signaling pathway and its associated immune responses and focused on the pathologic role of TLR4 in prostate carcinogenesis and tumor progression." (PMID 29928275, 2018). "The degree of hypoxia present in prostatitis is uncertain; however the current study suggests that activation of the TLR4 signaling pathway can lead to expression of VEGF, regardless of oxygen status, potentially augmenting disease progression." (PMID 23185615, 2012). "Toll-like receptor 4 (TLR4), a transmembrane receptor involved in immune/inflammatory responses (e.g., bacterial component recognition, cytokine regulation), is closely linked to prostatitis via inflammatory factors (e.g., IL-1β, TNF-α)." (PMID 40687578, 2025). "Their results indicated that TLR4 signalling may affect TGF-β1 signalling in prostatic epithelial cells and further promote development and progression of prostatic diseases." (PMID 27243216, 2016).
psoriatic arthritis (6 papers, 2014 to 2022). Joint inflammation associated with psoriasis. "There is also an association between chronic plaque psoriasis and psoriatic arthritis with polymorphisms in TLR4." (PMID 34215260, 2021). "We present data suggestive of an association between a functional variant and an intronic variant of TLR4 and chronic plaque type psoriasis and psoriatic arthritis." (PMID 26830904, 2016).
rectal cancer (6 papers, 2014 to 2023). A primary or metastatic malignant neoplasm that affects the rectum. "In rectal cancer, PA promotes TLR4 expression and tumor proliferation by promoting the expression of the transcription factor PU.1 upstream of TLR4." (PMID 36422271, 2022). "In our study, we similarly observed significant interactions on chromosome 9 in the 9q32-q33/TLR4 locus with smoking (rs1927911 AND rs11536889) and alcohol (rs1927911 OR rs11536889) on rectal cancer risk." (PMID 28956832, 2017). "By contrast, advanced rectal cancer with nodal metastases has decreased TLR4 expression compared with earlier stage rectal cancer (coef = −0.44, p = 0.079) (GSE12225)." (PMID 24887394, 2014). "Furthermore, data from Huang and colleagues (2018) showed improved DFS in people living with late-stage rectal cancer with increased activation of TLR4 via HGMB1 binding." (PMID 35841426, 2023).
renal cell carcinoma (6 papers, 2014 to 2024). "In renal cell carcinoma, miR-216a exerts tumor-suppressing functions by targeting TLR4." (PMID 31798627, 2019). "TIPE2 suppresses TLR4-mediated development of colon cancer by inhibiting caspase-8 activity, while its expression is positively correlated with TNM staging in renal cell carcinoma (RCC) patients." (PMID 25946186, 2015).
retinal degeneration (6 papers, 2012 to 2023). Degeneration of the retina. "The rd1 strain carries the retinal degeneration allele Pde6brd1 and the wild-type TLR4 allele and exhibits rapid rod photoreceptor death." (PMID 22615780, 2012). "There is a strong correlation between DIM-conserved markers in the brain and the proinflammatory molecules known to be cytotoxic in retinal degeneration, including Il-1α, Il-1β, Tnf-α, and Tlr4, as well as NO and ROS production." (PMID 36779012, 2023). "Deletion of TLR4 resulted in milder retinal degeneration in this model, which concluded that endogenous ligand release from photoreceptor injury/death triggers retinal inflammation via TLR4 signalling activation." (PMID 38983565, 2022). "In agreement with our findings, activated CAPN5 induced increased inflammatory factors through TLR4/6 autoimmunity inflammation pathways in retinal degeneration in ADNIV patients." (PMID 29245980, 2017). "Our results using a CD14-blocking antibody and a recent report that subretinal MP accumulation is TLR4 dependent in a retinal degeneration model back the notion that TLR signaling is involved in the alteration of the immunosuppressive environment." (PMID 25604058, 2015). "Because damage and death of photoreceptors is a major cause of retinal degeneration diseases, our results implicate TLR4 in regulating photoreceptor death during retinal degeneration by interfering with the neuroprotective activity of Wnt signaling." (PMID 22615780, 2012). "Next, the expression of TLR4 during photoreceptor death was analyzed using the C3H/HeOuJ mouse model of retinal degeneration (also known as rd1)." (PMID 22615780, 2012). "In addition, in mouse models of retinal degeneration, TLR4 activation by photoreceptor proteins contributed to an increase in subretinal monocytes/microglia, pro-inflammatory cytokine production, and retinal degeneration." (PMID 34445096, 2021). "Furthermore, the distribution of TLR4 in the photoreceptor layer changed during retinal degeneration and it became detectable in the outer nuclear layer, where the photoreceptor soma and nuclei are located." (PMID 22615780, 2012).
rosacea (6 papers, 2021 to 2026). A chronic erythematous skin disorder that affects the face. "Future investigations should be conducted to elucidate specific mechanisms underlying minocycline-induced downregulation of TLR4 expression in rosacea." (PMID 40378103, 2025). "When TLR4 was overexpressed, an aggravation of the inflammation manifestation and an increase in inflammatory infiltrating cells were observed in rosacea-like mice treated with minocycline." (PMID 40378103, 2025). "Minocycline alleviates inflammation progression in rosacea by downregulating TLR4 and inhibiting the activation of the NF-κB pathway, providing a scientific basis for subsequent clinical treatment." (PMID 40378103, 2025). "Our findings indicate that minocycline modulates rosacea development via the TLR4-mediated NF-κB signaling pathway." (PMID 40378103, 2025). "The results revealed that minocycline effectively suppressed the expression levels of inflammatory cytokines as well as TLR4 and p-NF-κB in LL-37-treated cells and rosacea-like mice." (PMID 40378103, 2025). "Following combined treatment with TLR4 overexpression and the NF-κB signaling pathway inhibitor PDTC, TLR4 expression remained unaltered in rosacea-like cells, while the p-NF-κB/NF-κB was significantly reduced." (PMID 40378103, 2025). "In order to better understand these outcomes, inflammatory and proinflammatory markers or their activators, such as TLR4, can be investigated in rosacea subtypes in future studies." (PMID 39064093, 2024). "Moreover, the effect of minocycline on rosacea was explored through the addition of an NF-κB inhibitor (PDTC) or overexpression of Toll-like receptor 4 (TLR4)." (PMID 40378103, 2025). "Furthermore, It is critical to emphasize that minocycline’s therapeutic effects on rosacea likely extend beyond TLR4/NF-κB modulation." (PMID 40378103, 2025). "Particularly higher TLR4 levels have been demonstrated in rosacea skin and ocular specimens." (PMID 39064093, 2024). "Specifically, TLR2 and TLR4 have been shown to be overexpressed in rosacea skin." (PMID 34322115, 2021). "Additionally, a study revealed that Dendrobium polysaccharides could inhibit the activation of the TLR4/NF-κB pathway in mouse skin, thereby reducing inflammation and exerting a protective effect against rosacea in mice." (PMID 40378103, 2025). "Compared to the NC group, upregulation of TLR4 and p-NF-κB/ NF-κB expression was observed in both LL37-treated HaCaT cells and skin tissue from rosacea-like mice, which was partially attenuated following minocycline treatment." (PMID 40378103, 2025). "Additionally, LA inhibited TLR4/nuclear factor (NF)-κB-regulated inflammation by binding to KLK5, thereby improving rosacea." (PMID 41668756, 2026). "In addition, both TLR4 expression and the p-NF-κB/NF-κB showed no marked changes in rosacea-like animal models." (PMID 40378103, 2025). "Besides TLR2, our RNA‐sequencing data also showed that other TLRs (e.g., TLR4, TLR7, and TLR8) were also significantly increased in rosacea, but the role of these TLRs remains unclear in the pathogenesis of rosacea." (PMID 33734592, 2021).
sarcoidosis (6 papers, 2009 to 2025). Sarcoidosis is a multisystemic disorder of unknown cause characterized by the formation of immune granulomas in involved organs. "Specifically, LYST, a regulator of endosome/lysosome trafficking, can regulate TLR3 and TLR4 mediated pathways, genes involved in the innate immune system which have been implicated in sarcoidosis." (PMID 39080656, 2024). "HLA-DRB1*0301/ DQB1*0201, transforming growth factor β (TGF-β), tumor necrosis factor α (TNF-α), and Toll-like receptor 4 (TLR-4) are all considered significant indicators for susceptibility to sarcoidosis." (PMID 32290254, 2020). "Conflicting reports about the association between TLR4 and sarcoidosis have recently been published." (PMID 21437199, 2011). "The long arm of chromosome 9, which harbors TLR4, was identified as a region related to the susceptibility to sarcoidosis by genome-wide microsatellite linkage analysis in a German population." (PMID 20011079, 2009). "Genetic polymorphisms within the TLR4 gene have been reported to be associated with various inflammatory diseases; therefore, TLR4 appears to be a susceptibility gene for sarcoidosis." (PMID 20011079, 2009). "This suggested that TLR4 polymorphisms were associated with sarcoidosis." (PMID 20011079, 2009). "Therefore, it was hypothesized that TLR4 and its ligands would be implicated in the development of sarcoidosis." (PMID 20011079, 2009). "TLR-2 and TLR-4 expression in blood mononuclear cells is significantly higher in patients with sarcoidosis than that in HCs." (PMID 41463010, 2025). "ABCC11 is a gene that influences macrophage differentiation and induces TNF-α and IL17 through TLR4 signaling; these results as well as the novel findings above support the importance of innate immune response genes in sarcoidosis." (PMID 39080656, 2024). "Baseline dectin-1, TLR2, TLR4 and MR mRNA expression in PBMCs was higher in patients with sarcoidosis than in healthy subjects (6-fold, 11-fold, 18-fold, and 4-fold, respectively)." (PMID 27688795, 2016). "Specifically, miR-146a-3p upregulated in progressive sarcoidosis is an indicator of inflammation and oxidative stress that may target TLR4 and was previously found elevated in sarcoidosis BALF, as well as serum." (PMID 39080656, 2024). "Our group also could not find any association between TLR4 polymorphisms and sarcoidosis in the Japanese population." (PMID 21437199, 2011). "We showed that PBMCs from patients with sarcoidosis had a higher mRNA expression of dectin-1, TLR2, TLR4 and MR at baseline." (PMID 27688795, 2016). "Our results demonstrated that PBMCs from patients with sarcoidosis had a higher in vitro baseline mRNA expression of dectin-1, TLR2, TLR4 and MR than healthy subjects." (PMID 27688795, 2016). "We showed that PBMCs from patients with sarcoidosis had a higher baseline mRNA expression of dectin-1, TLR2, TLR4 and MR (6-fold, 11-fold, 18-fold, and 4-fold, respectively)." (PMID 27688795, 2016).
sarcopenia (6 papers, 2017 to 2026). Progressive decline in muscle mass due to aging which results in decreased functional capacity of muscles. "Our results support a model in which TLR4/NF-κB axis signaling negatively regulates the expression of miR-532-3p and causes its downregulation in sarcopenia." (PMID 32226296, 2020). "This is the first study to examine the relationship between primary sarcopenia and serum TLR4, TLR9 and Resolvin E1 levels and to compare the biomarkers with SARC-F." (PMID 38910224, 2024). "Future studies can use TLR4‐defective C3H/HeJ mice as a model to investigate the role of TLR4 signaling on the development of sarcopenia." (PMID 28432254, 2017). "This FNDC5-ITGAVB5-FAK-mTOR-Bgn-TLR4 signaling axis was also validated in a sarcopenia mouse model." (PMID 41840428, 2026). "Serum TLR 9 and Resolvin E1 levels were statistically significantly higher in the sarcopenia group compared to the non-sarcopenia group (p < 0.001, p = 0.040), while TLR4 levels were higher in the sarcopenia group, but this increase was not statistically significant (p = 0.742)." (PMID 38910224, 2024). "The aim of this study was to evaluate the relationship between markers involved in different aspects of inflammation such as serum TLR4, TLR9 and Resolvin E1 levels and primary sarcopenia in geriatric patients and to compare the diagnostic accuracy of these biomarkers with the SARC-F score." (PMID 38910224, 2024). "Given that the majority of proinflammatory cytokine genes are controlled by TLR4/NF-κB axis signaling, we speculated that this pathway would be activated in the sarcopenia patient samples." (PMID 32226296, 2020). "Therefore, chronic inflammation by modulating TLR4 signaling may be a key factor for development of sarcopenia." (PMID 28432254, 2017). "At the muscular level, LPS can bind to Toll-like receptor 4 (TLR4), triggering the activation of the ubiquitin–proteasome system, thereby promoting sarcopenia." (PMID 40565245, 2025). "We found that the protein levels of TLR4, MyD88 and TRAF6 were significantly increased in three sarcopenia muscle samples, while those of the two NF-κB subunits, p50 and p65 were not increased." (PMID 32226296, 2020).